BPY2B (basic charge Y-linked 2B)
Synonyms: VCY2B
Gene: Protein-coding gene on chromosome Y (24,607,560 to 24,639,207, forward strand). Ensembl gene ENSG00000183795.
Gene Ontology:
Molecular function: HECT domain binding; protein binding
Biological process: spermatogenesis; single fertilization
Cellular component: nucleus
Homologues: Paralogues in human: BPY2 (100% identical), BPY2C (100% identical).
Diseases named in the same sentence as BPY2B in open-access papers:
BPY2B is named in the same sentence as 1 disease in open-access papers, as found by Europe PMC text mining. Sharing a sentence is not in itself a finding about the gene and the disease.
BPY2B shares sentences with these, for which no sentence is quoted: male infertility (1 paper).